HMGN4 (high mobility group nucleosomal binding domain 4)
Synonyms: HMG17L3; NHC
Tractability: PROTAC: ubiquitination databases record sites on it; its protein half-life has been measured.
Gene: Protein-coding gene on chromosome 6 (26,538,351 to 26,546,937, forward strand). Ensembl gene ENSG00000182952.
Subcellular location: Nucleus
Subcellular location (Human Protein Atlas): Nucleoplasm; Nucleoli
Gene Ontology:
Molecular function: protein binding; chromatin binding; nucleosomal DNA binding
Biological process: chromatin organization
Cellular component: nucleus; chromatin
Genetic constraint (gnomAD): Loss-of-function variants: 0 observed, 1.01 expected, observed/expected ratio (o/e) 0, 90% interval 0 to 1.72. That is too few expected variants to judge how well the gene tolerates losing a copy. Missense variants: 69 observed, 107.83 expected, observed/expected ratio (o/e) 0.64, 90% interval 0.53 to 0.78. Synonymous variants: 39 observed, 41.62 expected, observed/expected ratio (o/e) 0.94, 90% interval 0.72 to 1.22.
Homologues: Orthologues: macaque HMGN4 (100% identical), pig HMGN4 (90% identical), dog HMGN4 (87% identical), tropical clawed frog hmgn2 (70% identical), zebrafish hmgn2 (57% identical). Paralogues in human: HMGN2 (87% identical), HMGN3 (56% identical), HMGN1 (52% identical).
Diseases named in the same sentence as HMGN4 in open-access papers:
HMGN4 is named in the same sentence as 8 diseases in open-access papers, as found by Europe PMC text mining. Sharing a sentence is not in itself a finding about the gene and the disease. The quoted sentences say what the papers report.
hepatocellular carcinoma (3 papers, 2020 to 2025). A malignant tumor that arises from hepatocytes. "HMGN4 can be a promising candidate biomarker for hepatocellular carcinoma." (PMID 35979430, 2022). "In patients with hepatocellular carcinoma (HCC), elevated level of HMGN4 expression is associated with high grade tumors and shorter overall survival, suggesting that in patients with HCC, HMGN4 could act as a candidate biomarker for poor prognosis." (PMID 31936777, 2020).
thyroid cancer (2 papers, 2020 to 2022). "Previous studies have only shown that the upregulation of HMGN4 was related to the occurrence of thyroid cancer and hepatocellular carcinoma." (PMID 33247215, 2020).
gastric cancer (1 paper, 2024). A primary or metastatic malignant neoplasm involving the stomach. "High rates of expression of HMGB3, HMGN1, HMGN2, HMGN3, and HMGN4 are shown in gastric cancer." (PMID 39062899, 2024).
triple-negative breast carcinoma (1 paper, 2022). An invasive breast carcinoma which is negative for expression of estrogen receptor (ER), progesterone receptor (PR), and human epidermal growth factor receptor 2 (HER2). "HMGN4 plays a critical function in STAT3-mediated carcinogenesis in triple-negative breast cancer (TNBC) and it may well be a potential new focus for anti-TNBC therapy." (PMID 36568211, 2022).
tumor (5 papers, 2021 to 2024). "Additionally, RT‐qPCR analysis indicated that CHST9 was expressed at low levels in tumour samples, while HMGN4, ITGAV, RAP2A, TMCO3, and ZFYVE26 displayed high expression levels." (PMID 39428564, 2024). "HMGN4 upregulation in mouse and human cells and the thyroid gland of transgenic mice alters cellular transcriptional profiles, downregulates the expression of the tumor suppressors, including Atm, Atrx, and Brca2, and elevates the level of the DNA damage-marker, γH2AX." (PMID 36568211, 2022). "Notably, CRISPR–Cas9 knockout screening of HMGN4 in CCLE lines yielded a positive score, suggesting tumor suppressing functions of HMGN4 (Data not shown)." (PMID 34285249, 2021).
neurodegenerative disease (1 paper, 2024). A disorder of the central nervous system characterized by gradual and progressive loss of neural tissue and neurologic function. "Although HMGN4, KDM5D, and RBBP4 have not been directly correlated with PD, the dysregulation of chromatin-modifying complexes has been implicated in various neurodegenerative diseases, including PD." (PMID 38279299, 2024).
HMGN4 also shares sentences with these, for which no sentence is quoted: Obesity (1 paper); thyroid (1).